RNU1-72P (RNA, U1 small nuclear 72, pseudogene)
Gene: Small nuclear RNA gene on chromosome 7 (129,484,504 to 129,484,656, forward strand). Ensembl gene ENSG00000199846.
Homologues: Orthologues: chimpanzee U1 (98% identical), macaque U1 (95% identical), guinea pig U1 (83% identical), dog U1 (74% identical), dog U1 (71% identical), rat LOC120102679 (71% identical), mouse Gm23485 (67% identical). Paralogues in human: RNU1-89P (86% identical), RNU1-1 (85% identical), RNU1-2 (85% identical), RNU1-27P (85% identical), RNU1-28P (85% identical), RNU1-3 (85% identical), RNU1-39P (85% identical), RNU1-4 (85% identical), RNVU1-18 (85% identical), RNVU1-29 (85% identical), U1 (85% identical), RNU1-11P (84% identical), and 134 more.